CD4 (CD4 molecule)
Diseases named in the same sentence as CD4 in open-access papers (continued):
Sharing a sentence is not in itself a finding about the gene and the disease.
Allergy (continued). "Our results indicated that H2O2 resulted in a dose-dependent phosphorylation of p38 MAPK in CD4+CD25high Tregs from paediatric and adult subjects without allergy." (PMID 34072455, 2021). "The surface marker expression of CD4+ T cells in paediatric subjects with or without allergy was determined by flow cytometric analysis." (PMID 34072455, 2021). "In the current study, in children with evidence of sensitization to peanut (positive skin prick test) and/or peanut-specific IgE) and allergy confirmed in many on DBPCOFC, we determined if expression of CYP11A1 was increased in peripheral blood CD4+ T cells from PA children." (PMID 32497050, 2020). "After manual gating of CD4+ T, CD8+ T and NK cells according to S. Figure IIA, there was a reduction of TNF-α + IFN-γ+, IL-2+ cells in both allergy groups, reaching statistical significance only in the IgEneg allergy group." (PMID 32698761, 2020). "In contrast, markers of immune maturation, such as the number of CD4+ T cells/mL blood and the proportion of T cells expressing the memory marker CD45RO or the homing receptor CCR4, appeared furthest away from the allergy diagnosis at either 3 or 8 years of age (respectively)." (PMID 33007868, 2020). "When CD4 subsets are expressed as a ratio of one cell subtype to another within each subject, there is an increase in the ratio of Th2:Th17 cells in SLT patients, consistent with the observed findings of increased infection and allergy rate in the SLT cohort." (PMID 32868758, 2020). "CD4+FOXP3+ regulatory T cells (Tregs) are a subset of CD4+ T helper cells present in lymphoid and non-lymphoid tissues, and are crucial for mediating tolerance to self, preventing allergies and controlling immune reactions after infections." (PMID 30740105, 2019). "In addition, allergy immunotherapy led to a significant decrease in ER stress and PERK/CHOP signaling, increasing CD4+CD25+Foxp3+ Treg cells, and ameliorated airway hyper-responsiveness and airway inflammation." (PMID 29784924, 2018). "The pregnant women exposed to nevirapine with CD4 > = 250 cells/mm3 did not present a higher occurrence of hepatic alteration (p = 1.00) or ART medication-related allergic reaction (p = 1.00) (data not shown)." (PMID 30261855, 2018). "In this study we demonstrate the skewing of specific TCRs during the development of Pd allergy and the contribution of CD8+ T cells, rather than CD4+ T cells, to the development of this allergy in mice." (PMID 28561797, 2017). "Indeed, in our models, we found an increase in the proportion of Foxp3+ CD4+ Tregs following OIT, which was similar to other reports employing different models of allergic disease; notably, this increase was markedly enhanced by OIT+kakkonto." (PMID 28107533, 2017). "Th9 cells, a new member of CD4+ T cell family which is characterized by its specific cytokine IL-9 and transcription factors PU.1 and IRF-4, have been known recently to have a critical role in allergic diseases and cancers as well as the parasitic infection." (PMID 26509179, 2015). "Using HLA class II-peptide tetramer technology, naïve Bos d 2-specific T cells of PBMC cultures of individuals with or without allergy were of similar frequency, whereas the frequency of CD4+, CD45RO+ memory cells appeared to be higher in subjects with allergy." (PMID 24904583, 2014). "In an in vitro study, treatment with PCB-118, but not PCB-153, led to a shift in the differentiation of CD4+ T lymphocytes toward a T-helper 2–dominated response, which is consistent with allergic disease." (PMID 24162035, 2014). "Therefore, we induced airway allergic disease in Foxp3gfp.KI mice and sorted CD4+ T cells expressing Foxp3-GFP+ Treg cells and CD4+GFP− T cells (Foxp3−) present in the lungs." (PMID 22162718, 2012).
Allergy (continued). "Both FOXP3+CD4+CD25+ regulatory T (Treg) cells and inducible IL-10- and TGF-β-producing type 1 Treg (Tr1) cells may prevent the development of allergic diseases and play a role in successful allergen-SIT and healthy immune response via several mechanisms." (PMID 22409879, 2012). "Furthermore, whether and how repeated environmental exposure to allergens remodels lung CD4+ TRM cells and influences airway allergic disease is unclear." (PMID 39965565, 2025). "Moreover, extracellular vesicles containing catabolic enzyme arginase-1 suppressed proliferation of both CD4+ and CD8+ cells, signaling the importance of this amino acid in T cell responses and suggesting a new potential drug target in asthmatic allergic diseases." (PMID 34394086, 2021). "Importantly, T-cells not CD4+ T-cells are involved in an allergic reaction and an allergic reaction is stimulated by type 2 T helper cell along with immunoglobulin E." (PMID 33147821, 2020). "Some studies suggest that the number and function of CD4+CD25+ TRegs is not impaired in patients with allergies, whereas other reports indicate that a decreased number of CD4+CD25+ Treg cells might be related to allergic disease." (PMID 31826046, 2018). "Yet, the central role of such cells is debated because IL-4 production upon re-stimulation has been shown to be restricted to CD4+GATA3+ T cells in patients with known atopy, suggesting that the role of TH2 responses in IgG4-RD might be confounded by concomitant allergic disease." (PMID 28348556, 2017). "IL-10 levels in the PPG-TLR2 innate immune pathway were lower in the offspring from the mothers with allergies than those from the mothers without allergies (P = 0.006), in agreement with the observations in CD4+CD25+FOXP3+T cells and the FOXP3/LGA3 expression profiles for these groups." (PMID 27646403, 2016). "Also neutrophils, T cells (CD4+ and CD8+) and CD19+ B cells invaded the lungs of the allergy model." (PMID 27445696, 2016). "Children who outgrew their allergy (tolerant children) had higher frequencies of circulating CD4+CD25+ T cells and decreased in vitro proliferative responses to bovine beta-lactoglobulin in peripheral blood mononuclear cells compared with children who maintained clinically active allergy." (PMID 26023323, 2015). "In subjects without allergy, tetramer-positive CD4 T cells were barely detectable." (PMID 24904583, 2014). "For example, during antigen-mediated activation, CD4+ and CD8+ lymphocytes are able to produce hormones like ACTH, growth hormone (GH), thyroid stimulating hormone (TSH) and gonadotropins, which may regulate allergy progression." (PMID 20146826, 2010). "As well as inducing the Th2/TFH2/TFH13 axis, the severity of IgE-mediated allergies has been associated with functional impairment of non-follicular [Treg (CXR5-FoxP3+IL-10+) and Tr-1 (CXCR5-FoxP3-IL-10+)] and follicular [TFR (CXCR5+ FoxP3+IL-10+)] regulatory CD4+ T cells." (PMID 37954580, 2023). "Furthermore, concerning the connection between allergy development and balance in Th1 versus Th2 responses, miR-29 directly targets the TBX21 mRNA (also known as T-bet), the key transcription factor of Th1 cells, and miR-181-5p targets CD4, a co-receptor of the T cell receptor expressed on Th cells." (PMID 36999032, 2023). "In human memory CD4+ T cells, we also observed an increase in H3K4me3 and a decrease in H3K27me3 at the IL-10 promoter upon GSK3 inhibition, strengthening our suggestion that GSK3 inhibition may be a means of upregulating IL-10 production in autoimmune or allergic disease." (PMID 25627813, 2015). "In healthy donors, significant proliferation was observed in the CD4+CD25−, CD8+CD25−, and Tγδ cell fractions in response to chromium, indicating the presence of responsive T cell populations in the absence of allergic disease." (PMID 40004900, 2025).
Allergy (continued). "In addition, the up-regulation of GZMB expression by histamine in Th2-polarized CD4+ T cells, in CD4+ cells activated by IL-4 or in CD4+ T cells from AD patients indicates that this mediator of allergic inflammation may play a role in the homeostasis of the expression of GMZB in atopy and allergy." (PMID 37470818, 2023). "Although Tr1 cells with phenotypic characteristics of CD49b+ CD223+ and CD4+ are involved in oral unresponsiveness, we found no alteration in the numbers of Tr1 cells in the OIT group compared with the untreated allergy group." (PMID 33299086, 2021). "The TH2 allergy module was not preserved in the blood of mice challenged with HDM allergen, but only detectable in purified blood CD4+ effector T cells." (PMID 31253760, 2019). "Surprisingly, our observations indicated that reduced CD8+ but not CD4+ Tregs, especially CD45RA+CD8+ Tregs in both allergic patient groups, might also critically contribute to the pathogenesis of allergic diseases." (PMID 39592626, 2024). "Our findings were observed in global Cd226 KO mice and CD4+ T cell-specific Cd226 KO mice; however, we did not rule out the possibility that CD226 on other immune cells may play a critical role in the development of allergic reactions." (PMID 35846105, 2022). "Children with allergies had a lower number of PPG-stimulated CD4+CD25+FOXP3+T cells (P = 0.01), reduced FOXP3 expression in response to PPG and LPA (P = 0.02 and P = 0.01, respectively), and lower IL-10 production (P = 0.016), compared to the children without allergies." (PMID 27646403, 2016).
type 1 diabetes (310 papers, 2007 to 2026). "Our findings reveal early, cell-type-specific changes in transcription and gene regulatory networks in CD4+ T cells associated with type 1 diabetes progression, highlighting key pathways and transcriptional regulators." (PMID 41462339, 2025). "HERV-K18 encodes a superantigen known to stimulate CD4 +T cells, which is associated with the persistence of type 1 diabetes and EBV infection." (PMID 40719301, 2025). "To address this gap, we performed longitudinal scRNA-seq of CD4+ T cells isolated from PBMCs of children genetically at-risk of developing type 1 diabetes." (PMID 41462339, 2025). "The autoimmune destruction of β cells in type 1 diabetes is caused by the activation of diabetogenic T lymphocytes, including CD4+ T lymphocytes and CD8+ cytotoxic T lymphocytes (CD8+ CTLs)." (PMID 40716098, 2025). "In type 1 diabetes, insulin-reactive CD4+ T cells have been implicated in autoimmune pathophysiology." (PMID 40821816, 2025). "Type 1 diabetes (T1D) is an autoimmune disease characterized by insulin-secreting β cell destruction by CD4+ and CD8+ T cells, resulting in insulin deficiency and hyperglycemia." (PMID 38464515, 2024). "For example, type 1 diabetes (T1D)-associated variants were enriched in T cell caQTLs (activated CD4+ T logOR = 1.62, p = 0.017; naive CD8+ T logOR = 2.1, p = 0.030), where T cells are the critical cell type in the pathogenesis of T1D." (PMID 37289818, 2023). "At the 6q15 locus associated with type 1 diabetes, in line with previous reports, variant rs72928038 was a naïve CD4+ T cell caQTL linked to BACH2 and we validated the allelic effects of this variant on regulatory activity in Jurkat T cells." (PMID 37289818, 2023). "Type 1 diabetes (T1DM) is generally associated with insulin insufficiency due to the autoimmune destruction of pancreatic β-cells by CD4+ and CD8+ T cells and macrophages." (PMID 37513684, 2023). "Next, in a separate cohort we investigated CD4+ T-cell responses to the five C-peptide variants with individual Q to E substitutions in PBMC of people with recent onset type 1 diabetes." (PMID 36619657, 2023). "The type 1 diabetes-associated variants in UBASH3A in human CD4+ T cells resulted in higher levels of gene expression and decreased NF-kB signalling and IL2 expression." (PMID 37224769, 2023). "HLA-DQ8, a genetic risk factor in type I diabetes (T1D), presents hybrid insulin peptides (HIPs) to autoreactive CD4+ T cells." (PMID 34433824, 2021). "MSC-Exo-mediated suppression of Th1 and Th17 cells also showed beneficial effects in alleviation of streptozotocin-induced model of type-1 diabetes mellitus (STZ-T1DM) in which these inflammatory CD4+T cells play pathogenic role." (PMID 32456070, 2020). "Type 1 diabetes mellitus (T1D) develops as a result of pancreatic islet β-cells loss, mainly by means of CD4 T cells and other leukocytes action." (PMID 31191514, 2019). "In type 1 diabetes cross-linked peptides of proinsulin to other β-cell peptides (HIPs) were reported to be recognized by pathogenic CD4+ T cells." (PMID 31139178, 2019). "We have recently reported reduced incidence of type 1 diabetes in the NOD Stat5b transgenic mice associated with increased levels of CD4+ regulatory T cells, in which Stat5 plays a critical role." (PMID 23457589, 2013). "Previous research indicates that defects in the number and function of CD4+ T cell subsets might be the risk marker for Type 1 diabetes (T1D)." (PMID 39876913, 2024). "There was a lower percentage of CD3+CD4+ T lymphocytes secreting IL-4 in the study group, indicating that a deficiency in IL-4 production may be related to the development of type 1 diabetes." (PMID 36768715, 2023). "Studies have found that CD4 + memory T cells are associated with the onset of type 1 diabetes." (PMID 34122109, 2021). "However, there was a highly significant overlap between Type 1 diabetes (T1D)-associated loci and genes upregulated in CD4+ and CD8+ LPLs and CD8+ IELs." (PMID 24799394, 2015).
type 1 diabetes (continued). "The repeat at the CD4 locus has been associated with type I diabetes and vitiligo." (PMID 24818014, 2014). "Type 1 diabetes (T1D) is a chronic disease manifested by the loss of functional insulin producing β cells of pancreatic islets, caused by islet infiltrating self-reactive CD4+ and CD8+ T cells that mediate β-cell destruction." (PMID 23691523, 2013). "Interestingly, a type 1 diabetes study in mice demonstrated that T cells with a high expression of IR were aggressively diabetogenic, and a follow-up study determined that the pathogenic cells with high IR expression are predominantly memory CD4+ T cells." (PMID 40821816, 2025). "The phenotype of CD4+ T cells responsible for provoking autoimmunity varies depending on the disease but can broadly be divided into either T helper 17 (Th17) cells, involved in diseases such as multiple sclerosis (MS), or Th1 cells implicated in diseases such as Type 1 diabetes (T1D)." (PMID 39039893, 2024). "Furthermore, changes in the frequency of circulating activated T follicular helper and CXCR5–PD-1hi peripheral T helper cells and CD4+ Tregs have been observed in at-risk children who are positive for ≥2 islet-specific autoantibodies and newly diagnosed type 1 diabetes participants." (PMID 38714671, 2024). "In addition, we showed that the lower percentage of CD3+CD4+ T cells secreting IL-4 in patients with type 1 diabetes supports the idea that a deficiency in IL-4 production may be associated with the development of type 1 diabetes." (PMID 36768715, 2023). "Type 1 diabetes mellitus (T1DM) is a group of autoimmune diseases wherein autoreactive immune cells, especially CD4+ T cells, target pancreatic beta cells and cause complete insulin deficiency." (PMID 35255979, 2022). "Type 1 diabetes (T1D) is a chronic disease under complex environmental, immunological and genetic control, which is manifested by the autoimmune destruction of functional insulin-producing β cells of pancreatic islets caused by islet-infiltrating diabetogenic CD4+ and CD8+ T cells." (PMID 34447385, 2021). "Genetic association studies in type 1 diabetes have identified risk variants in the key genes responsible for autoimmune responses against insulin-derived peptides (HLA class II and class I genes, and the insulin gene), as well as in genes with prominent roles in CD4+ T cell function." (PMID 25652388, 2015). "IL-10 downregulates CXCR3 expression on CD4+ Th1 cells, and expression of this cytokine has been shown to be elevated in individuals with type 1 diabetes, specifically those who are older at onset." (PMID 41273416, 2026). "Type 1 diabetes (T1D) is driven by autoreactive CD4+ T-cell responses to pancreatic beta cell antigens presented by disease-associated human leucocyte antigen (HLA) class II molecules." (PMID 42278376, 2026). "TSCM cells have been linked to the development of adult T cell leukemia, to the survival of CD4+ cells latently infected with HIV-1 as well as to the development of type I diabetes." (PMID 40540506, 2025). "Overactivation of IRF4 has been associated with increased secretion of diabetogenic cytokines by CD4 + T cells, promoting the development of type 1 diabetes." (PMID 40597598, 2025). "Related to this, we have previously shown that Rapa MPs assembled with a CD4 peptide relevant for type 1 diabetes offer protection in a CD8-mediated mouse model of disease." (PMID 41183200, 2025). "Our study provides the first comprehensive single-cell analysis of CD4+ T cell transcriptome during the earliest phases of type 1 diabetes development—prior to both seroconversion and clinical diagnosis." (PMID 41462339, 2025). "Our study provides a comprehensive single-cell transcriptomic analysis of CD4+ T cells during the early, preclinical stages of type 1 diabetes in a homogeneous cohort of fast-progressing children." (PMID 41462339, 2025).